CIMIP2C (ciliary microtubule inner protein 2C)
Description:
Microtubule inner protein (MIP) part of the dynein-decorated doublet microtubules (DMTs) in cilia axoneme, which is required for motile cilia beating. Binds to the intra-tubulin interfaces (By similarity).
Synonyms: C2orf70; FAM166C; LOC339778
Tractability: Small molecule: a structure with a bound ligand is known.
Gene: Protein-coding gene on chromosome 2 (26,562,585 to 26,579,532, forward strand). Ensembl gene ENSG00000173557.
Subcellular location: Cytoplasm, cytoskeleton, cilium axoneme; Cytoplasm, cytoskeleton, flagellum axoneme
Subcellular location (Human Protein Atlas): Nuclear membrane; Vesicles
Gene Ontology:
Biological process: flagellated sperm motility
Cellular component: axonemal microtubule; nucleus; axonemal A tubule inner sheath; sperm flagellum; axoneme; cilium; microtubule cytoskeleton
Genetic constraint (gnomAD): Loss-of-function variants: 20 observed, 18.77 expected, observed/expected ratio (o/e) 1.07, 90% interval 0.75 to 1.54. The upper end of that interval is the gene's LOEUF score, 1.54, which puts it in group 6 of 6, group 1 being the genes least tolerant of losing a copy. Missense variants: 264 observed, 254.16 expected, observed/expected ratio (o/e) 1.04, 90% interval 0.94 to 1.15. Synonymous variants: 109 observed, 100.94 expected, observed/expected ratio (o/e) 1.08, 90% interval 0.92 to 1.27.
Homologues: Orthologues: chimpanzee C2AH2orf70 (99% identical), macaque CIMIP2C (96% identical), pig CIMIP2C (79% identical), dog CIMIP2C (79% identical), guinea pig CIMIP2C (78% identical), mouse Cimip2c (68% identical), rat Cimip2c (67% identical).
Diseases named in the same sentence as CIMIP2C in open-access papers:
CIMIP2C is named in the same sentence as 3 diseases in open-access papers, as found by Europe PMC text mining. Sharing a sentence is not in itself a finding about the gene and the disease.
CIMIP2C shares sentences with these, for which no sentence is quoted: lymphoma (1 paper); neuroblastoma (1); renal cell carcinoma (1).